MINAR2 (membrane integral NOTCH2 associated receptor 2)
Description:
Binds cholesterol and may regulate the distribution and homeostasis of cholesterol in hair cells. May play a role in angiogenesis.
Synonyms: KIAA1024L; DFNB120
Tractability: Antibody: UniProt predicts a signal peptide or a membrane-spanning region.
Gene: Protein-coding gene on chromosome 5 (129,748,094 to 129,766,732, forward strand). Ensembl gene ENSG00000186367.
Subcellular location: Lysosome membrane; Endoplasmic reticulum membrane
Gene Ontology:
Molecular function: cholesterol binding; protein binding
Biological process: angiogenesis; cholesterol homeostasis
Cellular component: endoplasmic reticulum; lysosomal membrane; endoplasmic reticulum membrane
Genetic constraint (gnomAD): Loss-of-function variants: 19 observed, 14.61 expected, observed/expected ratio (o/e) 1.3, 90% interval 0.9 to 1.82. The upper end of that interval is the gene's LOEUF score, 1.82, which puts it in group 6 of 6, group 1 being the genes least tolerant of losing a copy. Missense variants: 258 observed, 207.52 expected, observed/expected ratio (o/e) 1.24, 90% interval 1.12 to 1.38. Synonymous variants: 86 observed, 72.89 expected, observed/expected ratio (o/e) 1.18, 90% interval 0.99 to 1.41.
Homologues: Orthologues: chimpanzee MINAR2 (98% identical), macaque MINAR2 (95% identical), rabbit MINAR2 (86% identical), pig MINAR2 (82% identical), rat Minar2 (81% identical), dog MINAR2 (81% identical), guinea pig MINAR2 (81% identical), mouse Minar2 (81% identical), tropical clawed frog minar2 (47% identical), zebrafish minar2 (22% identical). Paralogues in human: MINAR1 (34% identical).
Diseases named in the same sentence as MINAR2 in open-access papers:
MINAR2 is named in the same sentence as 10 diseases in open-access papers, as found by Europe PMC text mining. Sharing a sentence is not in itself a finding about the gene and the disease. The quoted sentences say what the papers report.
Autosomal Recessive Deafness (2 papers, 2022). "Previous mouse genetic screening for hearing loss genes showed that Kiaa1024L/Minar2 knockout causes profound deafness." (PMID 36317962, 2022). "Loss of Kiaa1024L/Minar2, a previously understudied gene, caused deafness in mice, but how it functioned in the hearing was unclear." (PMID 36317962, 2022). "In conclusion, audiological findings both in humans and mice show that loss of MINAR2 function results in early-onset and sensorineural HL that rapidly progresses to severe to profound deafness." (PMID 35727972, 2022). "Here we report on DNA variants in MINAR2, encoding membrane integral NOTCH2-associated receptor 2, in four families underlying autosomal recessive nonsyndromic deafness." (PMID 35727972, 2022). "Indeed, while this study was under review, it was reported that mutations in MINAR2 cause deafness in human patients." (PMID 36317962, 2022). "A recent study revealed that mutations in MINAR2 also cause deafness in humans." (PMID 36317962, 2022). "For instance, in mice, loss of the Minar2 gene causes profound deafness." (PMID 36317962, 2022). "To support causality of the MINAR2 mutations in deafness and to begin understanding the mechanism of HL, we show that Minar2tm1b/tm1b mice have a severe, progressive increase in ABR thresholds from 2 wk old onwards (around the time that mice start to hear), with very few responses by 4 wk old." (PMID 35727972, 2022). "On the other hand, overexpression of the two MINAR2 deafness variants in families 1 and 2 does not show this effect, again supporting their loss of function." (PMID 35727972, 2022).
diabetes (1 paper, 2023). "Aside from Raptor, Minar2 interacts with a range of other proteins, which are associated with diabetes, metabolism, and the body mass-index." (PMID 37245847, 2023).
hearing loss (1 paper, 2025). "MINAR2 knockout results in rapidly progressive sensorineural hearing loss (SNHL) in mice and zebrafish models." (PMID 41130944, 2025). "WES revealed a homozygous novel LoF variant in MINAR2 that explains the isolated hearing loss phenotype observed in this patient." (PMID 41130944, 2025).
Impaired glucose tolerance (1 paper, 2023). An abnormal resistance to glucose, i.e., a reduction in the ability to maintain glucose levels in the blood stream within normal limits following oral or intravenous administration of glucose. "Minar2 KO mice on a high-fat diet develop obesity and impaired glucose tolerance and metabolism." (PMID 37245847, 2023).
Lewy body dementia (1 paper, 2025). A progressive form of dementia characterized by the presence of protein deposits called Lewy bodies in the midbrain and cerebral cortex, and loss of cholinergic and dopaminergic neurons. "In patients with Lewy body dementia, MINAR2 was shown to be downregulated in the frontal lobe brain, consistent with the phenotype of the MINAR2-knockout mice." (PMID 41130944, 2025).
Obesity (1 paper, 2023). Accumulation of substantial excess body fat. "•Inactivation of Minar2 in mice predisposes mice to diet-induced obesity." (PMID 37245847, 2023). "To investigate whether Minar2 KO mice are susceptible to diet-induced obesity, we challenged Minar2 KO and littermate control WT mice with a high-fat diet (HFD) and monitored their weight gain and food consumption over five weeks." (PMID 37245847, 2023). "Impaired expression or activation of MINAR2 could lead to obesity and obesity-associated diseases." (PMID 37245847, 2023). "In this study, we demonstrate that the inactivation of Minar2 in mice results in a dramatic effect on diet-induced obesity." (PMID 37245847, 2023). "Our findings identified Minar2 as a novel physiological negative regulator of mTORC1 with a key role in obesity and metabolic disorders." (PMID 37245847, 2023). "To investigate the role of Minar2 in obesity, we examined the expression of Minar2 in the adipose tissue of mice feed on chow diet." (PMID 37245847, 2023). "To study the role of MINAR2 in obesity, we examined a recently developed whole-body homozygous Minar2 knockout (KO) mouse where the exon two of Minar2 was replaced with the lacZ gene." (PMID 37245847, 2023). "Given the central role of mTOR signaling in metabolism and obesity, we decided to investigate the functional importance of Minar2 interaction with Raptor and its implication in mTOR signaling." (PMID 37245847, 2023). "Altogether, these data indicate that the inactivation of Minar2 in mice increases fat cell mass, which could lead to obesity." (PMID 37245847, 2023). "In conclusion, we have found that Minar2 plays a critical role in adipocyte expansion and obesity." (PMID 37245847, 2023). "•Minar2 KO mice on high-fat diet develop obesity and display impaired glucose metabolism." (PMID 37245847, 2023). "More importantly, given that Minar2 is expressed in various brain compartments it remains to be investigated, whether expression of Minar2 in the brain plays a particular role in the observed phenotype of Minar2 KO mice in obesity." (PMID 37245847, 2023). "Minar2 is a physiological negative regulator of mTORC1 with a major role in obesity." (PMID 37245847, 2023). "Minar2 regulation of mTORC1 via its interaction with Raptor, could be responsible, in part, for the diet-induced obesity observed in Minar2 KO mice." (PMID 37245847, 2023). "Unlike Minar2 KO mice, adipose-specific Raptor knockout mice, which positively regulates mTORC1 activity, results in lean mice that are resistant to diet-induced obesity." (PMID 37245847, 2023).
Parkinson disease (1 paper, 2023). A progressive degenerative disorder of the central nervous system characterized by loss of dopamine producing neurons in the substantia nigra and the presence of Lewy bodies in the substantia nigra and locus coeruleus. "Our previous studies revealed that loss of Minar2 in mice impairs motor function and results in Parkinson's disease-like symptoms." (PMID 37245847, 2023). "Emerging evidence now indicates that mTOR and autophagy are critical aspects of the pathogenesis of Parkinson disease, suggesting that deregulation of Minar2-mediated mTORC1 activity could, in part, also account for the observed impaired motor function in Minar2 KO mice." (PMID 37245847, 2023).
sensorineural hearing loss (1 paper, 2022). "Via a genetic approach conducted in families with sensorineural hearing loss, this study presents MINAR2 as an indispensable element of hearing in humans." (PMID 35727972, 2022).
MINAR2 also shares sentences with these, for which no sentence is quoted: autosomal recessive deafness-120 (1 paper); metabolic disorders (1).